IL10 (interleukin 10)
Diseases named in the same sentence as IL10 in open-access papers (continued):
Sharing a sentence is not in itself a finding about the gene and the disease.
tumor (continued). "Similar outcomes as well as reduced IL-10 expression were also observed in splenetic MDSCs of LLC tumor-bearing mice." (PMID 38402237, 2024). "Interleukin-10 (IL-10) is another prominent immunosuppressive and anti-inflammatory cytokine that is a key mediator of immune regulation secreted in the tumor microenvironment." (PMID 38493153, 2024). "C1qtnf6/Ctrp6, a member of C1q/TNF-related protein (CTRP) family, was demonstrated to increase the synthesis of IL-10 macrophages and promote tumor neovascularization." (PMID 38994368, 2024). "These signals can promote either a pro-tumor M2 phenotype (e.g., IL-4, IL-10, TGF-beta, and CCL2) or can drive TAMs towards an anti-tumor M1 phenotype (e.g., IFN-gamma and TNF-alpha)." (PMID 38730679, 2024). "Astragaloside IV inhibits the secretion of IL-10 from tumor cells by downregulating the expression of STAT3 and NF-κB in tumor cells." (PMID 39085255, 2024). "Currently, IL-10, known for its immunosuppressive activities, is being tested in combination with chemotherapy and nivolumab, showing promise in enhancing anti-tumor cytotoxicity by CD8 T cells." (PMID 38785789, 2024). "Butyrate administration significantly decreased the tumor size and levels of the immunosuppressive markers (PD-L1 and IL-10), their regulators (NF-KB and STAT3), and cancer growth factor (VEGF and GDF-15) in cancer tissues." (PMID 38197259, 2024). "The average percentage of tumor cells expressing cC3 was 32.2% (SD 16.3) for IgG, 43.5% (SD 9.3) for anti-PD-1, 49.1% (SD 12.5) for anti-IL-10, and 56.9% (SD 14.2) for anti-PD-1 and anti-IL-10 combination treatment." (PMID 38429349, 2024). "For example, IL-10 expressed by TAMs can inhibit antigen presentation by downregulating MHC molecule expression in tumor cells." (PMID 39840050, 2024). "Chemotherapy has been shown to inhibit interleukin‐10 (IL‐10) production by Bregs and induce increased apoptosis in Bregs, potentially enhancing anti‐tumour immunity and improving the efficacy of chemotherapy." (PMID 38997802, 2024). "IL-10 is an immunoregulatory cytokine with its presence in tumors resulting in suppression of anti-tumor T cell responses and poor cancer progression." (PMID 38400933, 2024). "On the contrary, tumor β-catenin signaling disrupts cDC1 recruitment in melanoma, and tumor production of factors such as IL-10, IL-6, TGF-β, and PGE2 suppresses DC function and maturation." (PMID 38903502, 2024). "Both TGF-β and IL-10 have bi-directional functions, meaning that in the pre-neoplastic state or the early stage of carcinogenesis, they act as tumor suppressor genes that inhibit cell proliferation and induce apoptosis." (PMID 38543305, 2024). "Tumor cells secreted immunosuppressive cytokines such as interleukin-10 (IL-10), which dampened the activity of activated CTLs, facilitating tumor expansion and immune escape." (PMID 39138733, 2024). "Our group previously demonstrated that IL-10 blockade helps increase T-cell mediated tumor death in colorectal liver metastases dependent on both MHC class I and II antigen presentation." (PMID 38429349, 2024). "In TC, it was clear that the body responds to the tumor burden drastically both locally and systemically via the release of different immunosuppressive cytokines and markers such as IL-10, TNF-α, and iNOS which further support the tumor progression." (PMID 37612575, 2024). "IL-10, known for its ability to suppress the activity of effector T cells and antigen-presenting cells, plays a significant role in diminishing anti-tumor immunity." (PMID 38500876, 2024). "Tumor cells have high expression of VEGF, IL-10, and IL-6; these tumor cells also highly express STAT3." (PMID 38571491, 2024). "A meta-analysis demonstrated that IL10, a cytokine with anti-inflammatory properties, regulates immune responses within the tumor microenvironment, potentially affecting tumor progression and response to immunotherapies." (PMID 39336493, 2024).
tumor (continued). "The Wnt-β-catenin-IL-10 signaling axis in intestinal antigen-presenting cells responds to symbiotic flora, influencing levels of the suppressive cytokine IL-10 and pro-tumor inflammatory factors." (PMID 38646539, 2024). "In the TME, a pro-tumor M2 macrophage polarization is promoted and sustained by a marked increase in immunosuppressive cytokine IL-10, which induces cell growth by activating JAK/STAT3, a COX-2 inductor signaling pathway." (PMID 38334650, 2024). "There are many immunosuppressive factors, such as transforming growth factor β (TGF-β) and interleukin-10 (IL-10), in the area around the tumor." (PMID 39194667, 2024). "CMP-sialic acid synthase (CMAS) knockdown in PDAC revealed that sialic acids in tumor cells induce an immunosuppressive environment by increasing IL-10 secretion and CD206 expression." (PMID 39727942, 2024). "IL-10-mediated drug resistance is associated with the upregulation of STAT3 signaling and antiapoptotic protein Bcl-2 in tumor cells." (PMID 39003350, 2024). "IL-4 and IL-13, as well as IL-10, have been demonstrated to play important roles during primary tumor progression in mouse models of cancer." (PMID 39599846, 2024). "Ultimately, combining DNA antigens, chemokines, and IL-10 siRNA increases tumor protection as compared to studies delivering naked DNA as therapy." (PMID 37587290, 2024). "The other activated macrophage phenotype, M2-like TAMs, are switched on by Th2 cells cytokines such as IL-13, IL-10 and IL-4, leading to tumor progression, inducing angiogenesis and metastasis, and inhibiting the anti-tumor response." (PMID 39050852, 2024). "Conversely, IL-10 can also bolster anti-tumor immune responses under certain conditions, for example, by stimulating cytotoxic CD8+ T cells and reducing inflammation 68-71." (PMID 39132165, 2024). "According to the results of the literature review, we included the previously reported independent variables of high risk, such as IL-6, IL-10, LDH, KL-6, smoking history and suspension of anti-tumor therapy into the multivariate regression analysis." (PMID 38983925, 2024). "Cytokines secreted by T cells were assayed, including TNF-α, IL-10, and IL-4, associated with generating antitumor CTL responses and tumor immune surveillance." (PMID 39772073, 2024). "Immunoregulatory cytokines such as IL-4 and IL-10 polarize macrophages towards the M2 phenotype, which hinders antigen presentation and aids tissue repair and remodeling, thus promoting tumor progression." (PMID 38673829, 2024). "Cytokines including TGF-β, IL-6, and IL-10 promote tumor development by inhibiting efficient immune surveillance." (PMID 39767682, 2024). "The potential anti-tumor effects of IL-10 involve upregulating CD8+ T cells cytotoxicity, thereby reducing macrophage infiltration, increasing NK cell infiltration, resisting angiogenesis, and stabilizing intrinsic apoptosis." (PMID 38279997, 2024). "IL-10 has anti-inflammatory functions and supports tumor progression by limiting efficient antitumor response." (PMID 39635522, 2024). "IL-10+ TAM infiltration in GC tissue has been proven to yield an immune escape tumor microenvironment featured by regulatory T cell infiltration and CD8+ T cell dysfunction." (PMID 39525623, 2024). "M2 stimulates tumor growth and invasion through the secretion of IL-4, IL-13, IL-10, vitamin D3, and glucocorticoids." (PMID 39201801, 2024). "Circulating tumour cells (CTCs) and interleukin-1β (IL-1β), interleukin-6 (IL-6), interleukin-8 (IL-8), and interleukin-10 (IL-10) were measured in a pilot group of 40 patients at baseline and before cycle two (C2) and cycle three (C3)." (PMID 38398148, 2024). "High IL-10 levels are also associated with recruitment of Tregs to the TME, thus promoting immune evasion by the tumour cells." (PMID 38633747, 2024).
tumor (continued). "Fresh human FLC tumor slice cultures (TSCs) were treated with antibodies blocking programmed cell death protein-1 (PD-1) and interleukin-10 (IL-10), with results measured by cleaved caspase-3 immunohistochemistry." (PMID 38429349, 2024). "Factors such as the upregulation of PD-L1 on tumor cells and the secretion of immunosuppressive cytokines like IL-10 and TGF-beta inhibit CTL activation and proliferation." (PMID 39295859, 2024). "Specifically, they showed in vitro that tumor cells promote differentiation of macrophages into IL-10-producing macrophages, which in turn induced immune suppression by PD-L1 expression in tumor cells." (PMID 39053947, 2024). "This process ultimately leads to the over-expression of IL-10, thereby inhibiting the effective cytotoxic tumor-killing ability of NK cells." (PMID 39609700, 2024). "No or very low levels of other cytokines found post-TCE treatment such as interleukin (IL)-6 and IL-10 were detected in the tumor supernatant." (PMID 39261676, 2024). "PD-1 (programmed cell death protein-1)/PD-L1 (programmed cell death ligand 1) as well as IL-10 (interleukin-10)/IL-10R (interleukin-10 receptor) interactions play a major role in tumor immune evasion in various malignancies." (PMID 39325190, 2024). "Tumor cells secrete high levels of cytokines like IL-4, IL-10, and IL-13 that signal through STAT6 pathways and drive macrophages towards an M2 alternative activation state [1127,1128,1129]." (PMID 39273409, 2024). "Transfection of EBV IL-10 into murine melanoma cells resulted in palpable tumors in 4 weeks and a local immunosuppressive effect, with reduced tumor infiltration of CD4+ and CD8+ T cells." (PMID 39459945, 2024). "Myeloid cells promote tumor immune escape by releasing interleukin-10 (IL-10), which accumulates within mesenchymal-like tumor regions and results in T-cell depletion." (PMID 39506843, 2024). "This occurs by stimulating increased expression of indoleamine 2,3-dioxygenase (IDO) and interleukin-10 (IL-10), among other anti-inflammatory mediators, promoting a tumor microenvironment conducive to cancer survival." (PMID 39335494, 2024). "Mesenchymal cells also contribute to immune regulation within the tumor microenvironment by secreting immune-suppressive factors like IL-10 and TGF-β, which help the tumor evade immune surveillance." (PMID 39711950, 2024). "It was previously reported that the prognosis of cancer patients is inversely correlated with elevated serum and tumour IL-10 levels (Ref." (PMID 38186186, 2024). "In HCC, HMGB1 triggers M2 macrophage polarization through the TLR2/NOX2/autophagy axis, a transformation that promotes tumor growth via upregulation of IL-10 expression." (PMID 38529373, 2024). "In tumours, the most abundant myeloid cells activate Th2 cytokines, IL-10 and TGF-β, stimulate the arginase pathway, and suppress nitric oxide synthase (iNOS) expression." (PMID 39712018, 2024). "We further found that IL‐10 in xenograft tumours was downregulated in in the mice sh‐circ group compared to the NC group via IHC assay." (PMID 38506082, 2024). "Some immunosuppressive factors, such as IL-10, is considered immunosuppressive cytokine that promotes tumor cell proliferation and metastasis and can promote tumor progression by recognizing IL-10R on the surface of CD8+T cells and inhibiting T cell function." (PMID 38415245, 2024). "Typically, M1 macrophages play a pro-inflammatory role by expressing nitric oxide synthase (iNOS), while M2 macrophages express anti-inflammatory cytokines, such as IL-10, to promote tumor progression and metastasis." (PMID 38361757, 2024). "Regulatory T cells (Tregs) assist tumor cells in evading immune system responses by secreting immunosuppressive cytokines including IL-10 and TGF-β1." (PMID 38553754, 2024). "While IL10 is generally considered to be an anti-inflammatory cytokine that suppresses inflammation, it has been demonstrated to play a promoting role in tumor development." (PMID 38506672, 2024).
tumor (continued). "We conducted tumor treatment-related immune cell and Th1/Th2 subset detection in the patient, comparing the concentrations of 6 cytokines (IL-2, IL-4, IL-6, IL-10, TNF-α, and TNF-γ) and various immune cells in peripheral blood before and after treatment." (PMID 39871939, 2024). "Pro-inflammatory cytokines like IL-6 and TNF-α can promote tumor cell proliferation and survival, while anti-inflammatory cytokines such as IL-10 contribute to immune evasion." (PMID 39200315, 2024). "T-cell function was found to be rescued by inhibiting the JAK/STAT pathway, demonstrating that IL-10 release is an important driver of tumor immune escape." (PMID 38856921, 2024). "Through the enhancement of mitochondrial oxidative phosphorylation, IL-10 induces the expansion and effector function of exhausted tumor-infiltrating T cells." (PMID 38619641, 2024). "As a part of TGF-β signaling, TAMs have been observed to exert several pro-tumor effects through the secretion of immunosuppressive cytokines, including interleukin-10 (IL-10) and transforming growth factor-β (TGF-β)." (PMID 38730579, 2024). "They observed that the anti-VEGF drugs not only increased the content of CX3CL1 and CXCL5 in tumor vessels but also promoted the recruitment of neutrophils, resulting in the release of a large amount of the cytokine IL-10 to inhibit the adaptive immunity." (PMID 38534538, 2024). "Under the selective pressure of the immune system, the immunogenicity of the remaining tumor cells is further reduced by the production of immunosuppressive factors such as IL-10, TGF-β, PD-L1, and so on, resulting in immune escape." (PMID 38887597, 2024). "Under the stimulation of tumor progression, chemokines, and cytokines, such as IL-4 and IL-10, TAMs in the TME are mainly polarized toward M2 macrophages." (PMID 39263534, 2024). "It induces inflammation in the tumor niche, among others, due to a local decrease in the concentration of IL-10." (PMID 39057050, 2024). "Gene expressions for tumor promoting genes such as Arg1, Il6, Il10, Mmp9, Lgals9, and Vegfa were significantly decreased, whereas that of the tumor suppressive gene such as Il12 increased." (PMID 39702544, 2024). "M2d macrophages, known as tumor-associated macrophages (TAMs), upregulate IL-6, IL-10, TGF-β, VEGF, and PD-L1 expression while depleting arginine to suppress T cell anti-tumor functions." (PMID 39662177, 2024). "Specifically, TAMs inhibit T-cell activation and anti-tumor immune responses by secreting a series of cytokines and signaling molecules, such as IL-10 and TGF-β, thereby promoting tumor escape and drug resistance." (PMID 39697553, 2024). "IL24, part of the IL-10 cytokine family, is recognized as a tumor suppressor with significant anti-cancer properties." (PMID 39850884, 2024). "Conversely, M2 type TAMs accelerate tumor progression and invasion by secreting immune-suppressive factors like IL-10 and TGF-β." (PMID 38415252, 2024). "IL-10 promotes tumor growth in PCa by suppressing the antitumor immune response through its effects on immune cells and by directly acting on the PCa cells." (PMID 39202777, 2024). "IL-6, IL-10, and IL-4 are considered the main Th2 immune cytokines, mainly encouraging tumor growth by hindering the host’s immune system." (PMID 38361933, 2024). "Tumor endothelial cells induce immunosuppressive CD4+ T cells through IL-10 and TGFβ, contributing to tumor evasion." (PMID 39325128, 2024). "M2d macrophages promote tumour progression through two main mechanisms: First, M2d cells are capable of producing pro-tumourigenic factors such as IL-10 and TGF-β." (PMID 39060648, 2024). "Tendencies of enhancement in IL-12p70 (pro-inflammatory) secretion and reduction in IL-10 (anti-inflammatory) expression to surpass tumor-influences, are NLGP-induced features among dendritic cells." (PMID 38649988, 2024).
tumor (continued). "In tumour microenvironments, cancer cells increase B7-H4 expression in response to hypoxia and transforming growth factor β1 (TGFβ1); IL-6 and IL-10 can also stimulate B7-H4 mRNA expression in macrophages." (PMID 39571901, 2024). "Slit2 treatment further induced gene expression associated with a tumor-promoting macrophage phenotype by activating MMP-9, VEGF-a, Mrc1, Ccl19, TGF-β1, IL-10, Cd209a, and Arg1." (PMID 39456164, 2024). "In this context, an increase in IL-10 production would stimulate inflammation within the tumor microenvironment to promote tumor progression." (PMID 39057050, 2024). "IL-10 also plays a key role in reducing the proportion of cytotoxic T cells further resulting in pro-tumor remodeling of the TME." (PMID 38533720, 2024). "The immunosuppressive cytokines, TGF-β, IL-4, IL-10, and IL-35, are the cytokines that are dominant in the tumor environment in different tumors." (PMID 38850434, 2024). "extract that inhibited IL-10/Signal transducer and activator of transcription 3 (STAT3)/PD-L1 signaling pathway as well as shifted from the tumor-associated macrophages phenotype M2 to M1." (PMID 38500769, 2024). "Many studies have shown that STAT3 activation in tumor cells governs the secretion of diverse pro-inflammatory factors including IL-6, IL-10 and VEGF." (PMID 38245798, 2024). "Tumor cells secreting factors such as IL-6, TGF-β, and IL-10 perpetuate an inflammatory environment that supports tumor growth and suppresses antitumor immune responses." (PMID 39664377, 2024). "Some studies suggest that IL-10 suppresses cancer cells by stimulating CD8+ T cells, while other research indicates that IL-10 can lead to the stimulation of tumor cell proliferation." (PMID 38339076, 2024). "IL-10 expression was increased in macrophages affected by tumor-derived miR-6794-5p, and overexpression of IL-10 by miR-6794-5p increased cancer cell motility, invasiveness, and stemness." (PMID 38521953, 2024). "The other type mainly occurs in the process of tumor proliferation and metastasis, and macrophages induced by IL-4 and IL-10 are polarized to the M2-like phenotype, which is called M2-like tumor-associated macrophages." (PMID 39596288, 2024). "High levels of cholesterol PD and its association with low IL-6 and IL-10 levels, could reflect a low systemic inflammatory state (or a “good” chronic inflammation state) and might favorably condition the proficiency of the tumor microenvironment to respond to ICIs." (PMID 38989743, 2024). "Elevated IL-10 levels can stimulate tumor cell growth and proliferation, inhibit apoptosis, and facilitate immune evasion." (PMID 39519758, 2024). "These components interact through signaling molecules such as HIF-1α, Vascular Endothelial Growth Factor, IL-6, and IL-10, influencing tumor progression, immune evasion, and response to treatment in urological cancers." (PMID 38249783, 2024). "CD14 + CTLA-4+ tolerogenic DCs are a regulatory DC subtype that can suppress the anti-tumor immune response of CTLs via IL-10 and indoleamine-2,3-dioxygenas." (PMID 38791916, 2024). "Macrophages also play a crucial role in innate immunity and anti-cancer responses, with the pro-inflammatory M1 phenotype exhibiting anti-tumor effects, while the anti-inflammatory M2 phenotype supports tumor growth by releasing factors like IL-10 and TGF-β." (PMID 39346906, 2024). "The most advanced IL-10 therapy has been the treatment of cancer patients with a PEGylated recombinant human IL-10 (PEG-rHuIL-10), which has been shown to suppress tumour-associated immunity, improve clinical outcome." (PMID 39411713, 2024). "Egfl6+ tumor-infiltrating PMN-MDSCs were found to express higher levels of IL-10 than control tumors." (PMID 39312740, 2024). "CD5+ regulatory B cells are present in murine bladder cancer, while in prostate cancer, CD138+IgA+PD-L1+ B cells promote tumor progression by secreting the immunosuppressive cytokine IL-10." (PMID 39519376, 2024).